VTN (vitronectin)
Diseases named in the same sentence as VTN in open-access papers (continued):
Sharing a sentence is not in itself a finding about the gene and the disease.
mastitis (2 papers, 2021 to 2026). Inflammation of breast tissue during lactation or postpartum due to an obstructed duct or infection. "Findings from the study indicate that the inflammatory protein, vitronectin is over-expressed in both subclinical and clinical mastitis." (PMID 33509059, 2021). "Therefore, vitronectin is an important mediator in the onset of mastitis and can be considered as a valuable biomarker for diagnosis of the subclinical mastitis." (PMID 33509059, 2021). "Biomarkers such as lactoferrin (LTF), β-defensin 4 (DEFB4), vitronectin, paraoxonase 1 (PON1), and N-acetyl-β-D-glucosaminidase (NAGase) show promise in distinguishing between cows not susceptible and cows susceptible to mastitis." (PMID 41594349, 2026).
membranous nephropathy (2 papers, 2021 to 2022). "Another study also revealed an increased colocalization of MAC, VTN, and VTN receptor (avβ3 integrin), both of which are within and around the subepithelial deposits in membranous nephropathy." (PMID 35462789, 2022).
metastatic disease (2 papers, 2025). "COL3A1, COL5A2, VCAN, CCND2, JAG2, and VTN showed consistent positive correlations with all three scores in both primary and metastatic tumors, suggesting their involvement in enhancing stromal support and recruiting immune cells." (PMID 40943183, 2025). "The upregulation of genes encoding matrix associated factors including proteases and cell adhesion molecules such as ADAM12, NTN3, LRRC15, CDH17, PCDH19, VTN highlighted the relevance of the tumor microenvironment and cell–cell and cell–matrix interaction for progression to metastatic disease." (PMID 41402347, 2025). "VTN showed positive associations with CD4+ T cells and dendritic cells in metastatic tumors, but negative correlations with NK cells and eosinophils." (PMID 40943183, 2025).
multiple myeloma (2 papers, 2019 to 2023). "In drug resistant multiple myeloma cells, the adhesion signaling molecules, such as VTN, was upregulated by Notch signaling pathway and conferred cell protection from drug induced apoptosis." (PMID 30819137, 2019).
myocardial infarction (2 papers, 2011 to 2025). Gross necrosis of the myocardium, as a result of interruption of the blood supply to the area, as in coronary thrombosis. "Additionally, extracellular matrix (ECM) proteins, including vitronectin (VTN), plasminogen (PLG), and fibrinogen beta chain (FGB), displayed significant fold changes and were strongly associated with early myocardial infarction." (PMID 41399465, 2025).
nephritis (2 papers, 2015 to 2022). Inflammation of renal tissue. "Considering that an increase in PAI-1 and vitronectin could result in renal impairment, and even cause a nephritis-like response, pledges for further evaluation of interaction between ανβ3 integrin, PAI-1, vitronectin and hantaviruses." (PMID 25852676, 2015). "Coincidentally, it is reported that the high levels of VTN are associated with the circulating immune complex- (CIC-) soluble membrane attack complex (MAC) in SLE patients with active nephritis, implying the possible value of VTN in active nephritis." (PMID 35462789, 2022).
non-small cell lung carcinoma (2 papers, 2016 to 2018). A group of at least three distinct histological types of lung cancer, including non-small cell squamous cell carcinoma, adenocarcinoma, and large cell carcinoma. "Human non-small cell lung cancer tissue sections were assessed for the expression of vitronectin by immunohistochemistry." (PMID 27484721, 2016). "Immunohistochemical staining of sections from non-small cell lung cancers showed that vitronectin was localized around blood vessels and in the tumor-stroma interface." (PMID 27484721, 2016). "By comparing non-small cell lung cancer patients, who had developed a grade ≥ 2 radiation-induced lung toxicity (RILT) after receiving radiotherapy, with those who did not receive radiotherapy, higher expression level of vitronectin (VTN) was found in the plasma (p = 0.02)." (PMID 29661186, 2018).
rheumatoid arthritis (2 papers, 2018 to 2024). A chronic, systemic autoimmune disorder characterized by inflammation in the synovial membranes and articular surfaces. "Importantly, abciximab directly targets vitronectin, whereas fostamatinib has drawn attention for its reported safety and efficacy in phase 3 clinical trials for the treatment of patients with rheumatoid arthritis." (PMID 38734017, 2024).
sarcoidosis (2 papers, 2018 to 2023). Sarcoidosis is a multisystemic disorder of unknown cause characterized by the formation of immune granulomas in involved organs. "Higher expression of CD41b, a receptor for fibronectin, fibrinogen, plasminogen, prothrombin, thrombospondin and vitronectin, was reported in IPF patients compared to sarcoidosis and HP BAL samples." (PMID 36835481, 2023).
triple-negative breast carcinoma (2 papers, 2017 to 2025). An invasive breast carcinoma which is negative for expression of estrogen receptor (ER), progesterone receptor (PR), and human epidermal growth factor receptor 2 (HER2). "Similarly, blocking the interaction between tumor cell-secreted vitronectin (Vtn) and its receptor C1qbp on macrophages effectively counteracts the “don’t eat me” signal, augmenting tumor cell phagocytosis and suppressing triple-negative breast cancer progression." (PMID 41459510, 2025). "As a consequence of GDE3 action, uPAR loses its vitronectin-dependent and matrix-degrading activities, when assayed in HEK293-uPAR and triple-negative breast cancer cells that express both uPAR and uPA." (PMID 28849762, 2017).
uveal melanoma (2 papers, 1998 to 2014). A melanoma derived from melanocytes of the uveal tract. "In metastases of uveal melanomas, several proteins were found to be upregulated: Colony stimulating factor 2, Ficolin precursor, Haptoglobin -2 precursor, Hemopexin precursor, α-1-antitrypsin precursor, α-1-antichymotrypsin precursor, Vitronectin precursor, and Down syndrome cell adhesion molecule." (PMID 24392146, 2014).
astroglioma (1 paper, 2013). "The integrin substrates laminin, fibronectin and vitronectin, but not collagen, thrombospondin or fibrinogen, reduced CNTF expression in C6 astroglioma cells." (PMID 23693126, 2013).
autoimmune disease (1 paper, 2025). A disorder resulting from loss of function or tissue destruction of an organ or multiple organs, arising from humoral or cellular immune responses of the individual to their own tissue constituents. "Alpha-2-macroglobulin (A2M) and vitronectin (VTN), both involved in coagulation and fibrosis, represent targets for thrombotic and vascular complications in autoimmune diseases." (PMID 40142826, 2025).
benign ganglioneuroma (1 paper, 2022). "Thus, vitronectin was detected in normal matured peripheral neurons (i.e., pheochromocytes), as well in ganglion and Schwann cells (SCs) of adult benign ganglioneuroma (GN) tumors." (PMID 36231134, 2022).
breast ductal carcinoma in situ (1 paper, 2014). "Vitronectin was identified in an MS analysis comparing serum from breast ductal carcinoma in situ (DCIS) patients to healthy controls." (PMID 24713112, 2014).
Cerebral ischemia (1 paper, 2023). Restriction of arterial blood supply to the brain associated with insufficient oxygenation to support the metabolic requirements of the tissue. "Likewise, vitronectin has also been found to be increased in cerebral ischemia." (PMID 37175625, 2023).
cervical tumor (1 paper, 2024). "Third, further in-depth study of the mechanism of action of VTN in the cervical tumor microenvironment, especially its interaction network with other extracellular matrix proteins, growth factors, and signaling pathways are warranted to illustrate the potential regulatory mechanism." (PMID 39717749, 2024).
chronic hepatitis (1 paper, 2018). An active inflammatory process affecting the liver for more than six months. "Similarly, nonviral etiologies, LPS/D-GaIN-induced ALF, and chronic hepatitis cases could be justified by protein aggregates mediated by vitronectin or clusterin (complement regulatory proteins), limited to the measurement of the complement components." (PMID 30402508, 2018).
chronic kidney disease (1 paper, 2021). Impairment of the renal function secondary to chronic kidney damage persisting for three or more months. "Furthermore, in a murine model, kidney vitronectin mRNA and protein expression was higher in mice with chronic kidney disease than in controls, yet the same authors also found that vitronectin did not have an implication in fibrogenesis in a Vtn knock-out mice model." (PMID 33275196, 2021).
chronic lung disease (1 paper, 2018). According to the definitions of the American and British Thoracic Societies, including pulmonary functional tests, X-rays, and CT scans for items such as fibrosis, bronchiectasis, bullae, emphysema, nodular or lymphomatous abnormalities. "Vitronectin is also an effector associated with inflammatory processes, as evidenced by increased levels of the glycoprotein in the bronchial lumen of patients with chronic lung disease." (PMID 30061873, 2018).
chronic pancreatitis (1 paper, 2025). A chronic inflammatory process causing damage and fibrosis of the pancreatic parenchyma. "The expression of VTN was further influenced by a history of chronic pancreatitis, with past sufferers showing reduced levels." (PMID 40433359, 2025).
coagulopathy (1 paper, 2025). "Remarkably, main hub proteins in the CR group were VTN, C3, C4B, C9, and CFH that play a major role in the complementary pathway, which has gained increased attention as a major contributor to cancer‐related coagulopathy." (PMID 40079446, 2025).
colorectal adenoma (1 paper, 2024). An adenoma that arises from the colon or rectum. "A recent study found that serum biomarkers F5, ITIH4, LRG1, and VTN were elevated in colorectal adenoma patients as well as in a mouse model of colorectal adenomas." (PMID 38383428, 2024).
depression (1 paper, 2023). "Among them, the degree values of VTN, SPP1, plasminogen activator inhibitor 1 (SERPINE1), membrane spanning 4-domains a2, HIST2H2AC, and other genes were high in the whole network; therefore, these genes can be considered crucial for the development of depression." (PMID 37932972, 2023).
dry eyes (1 paper, 2021). "We investigated the expression and distribution of VTN in dry eyes." (PMID 34445121, 2021). "The pathological significance of αv integrins in the development of DED may be highlighted by increased VTN protein expression in dry eyes and in the therapeutic effect of c(RGDfK)." (PMID 34445121, 2021). "Our data revealed that the VTN protein was not restricted to the dry eye but could also be detected in the ocular tissues of NS mice, including the tear fluid and conjunctival stroma." (PMID 34445121, 2021). "In addition, qPCR and Western blot analysis of the VTN gene and protein expression in conjunctiva isolated from DED mice were 2.3-fold and 2.9-fold greater than the NS mice, respectively, suggesting that the local biosynthesis of VTN in the conjunctiva is stimulated in dry eyes." (PMID 34445121, 2021).
endocrine cancers (1 paper, 2025). "Further analysis of additional ECM molecules, including VTN, EMC1, THBS3, and CLEC3B revealed a positive correlation trend with PEBP1/STK11 co-expression in endocrine cancers, while correlations in other cancer types varied, suggesting a context-dependent relationship." (PMID 40806276, 2025).
epithelioid hemangioendothelioma (1 paper, 2021). A low-grade malignant blood vessel neoplasm. "(H) Vitronectin expression in epithelioid hemangioendothelioma (EHE) compared to epithelioid angiosarcoma (E–AS) and epithelioid hemangioma (EH)." (PMID 33913810, 2021). "In contrast, VTN was expressed in all EHE samples, but was essentially absent in epithelioid angiosarcoma and epithelioid hemangioma." (PMID 33913810, 2021).
fibrosarcoma (1 paper, 2021). A malignant mesenchymal fibroblastic neoplasm affecting the soft tissue and bone. "In another model system, PAI-1 hindered the adhesion of human fibrosarcoma cells to vitronectin and stimulated the migration of the cells from vitronectin to Collagen type IV." (PMID 35008762, 2021).
fungal infection (1 paper, 2014). "Targeting candida Gpm1 and blocking the Gpm1 vitronectin interaction may lead to a directed therapeutic approach to modulate or even block fungal infection." (PMID 24625558, 2014).
gestational diabetes (1 paper, 2020). Carbohydrate intolerance first diagnosed during pregnancy. "In a nested case-control proteomic analysis study, sera from 60 obese women with gestational diabetes mellitus (GDM) identified three candidate predictors of GDM: SAP, afamin, and vitronectin." (PMID 32967132, 2020).
giant cell arteritis (1 paper, 2024). "Therefore, considering their reasonable potential role in giant cell arteritis pathogenesis, either gene (VTN or SARM1) or a more intricate mechanism influencing both could underlie the observed association within this genomic locus." (PMID 38734017, 2024). "Additionally, three new genomic associations with giant cell arteritis were identified at the 8p21.1 (CCDC25, rs11782624; p=1·28 × 10–8; OR 1·18 [95% CI 1·12–1·25]), 15q26.1 (MFGE8, rs8029053; p=4·96 × 10–8; OR 1·19 [1·12–1·26]) and 17q11.2 (VTN, rs704; p=2·75 × 10–9; OR 0·84 [0·79–0·89]) regions." (PMID 38734017, 2024).
giardiasis (1 paper, 2023). An infection of the small intestine caused by the flagellated protozoan giardia lamblia. "In the liver, proteins upregulated during giardiasis included vitronectin (P29788), Ly6/PLAUR domain protein (Q9D7S0), complement factor B (P04186), and mucin-13 (P19467)." (PMID 36675151, 2023).
gynecological cancer (1 paper, 2016). "Its activation can be induced by inflammatory growth factors and cytokines controlling the gynecological cancer development by involving in the degradation of the matrix including its components, vitronectin, fibronectin and collagen type I, which contribute to cancer cell adhesion and invasion." (PMID 27902750, 2016).
heroin dependence (1 paper, 2014). Physical and psychological dependence on the drug heroin. "The 6 protein spots with an increase upon heroin dependence were identified as immunoglobulin J chain (spots 1 and 2), transthyretin (spot 3 and 7), haptoglobin (spot 4), and vitronectin (spot 6)." (PMID 24743330, 2014).
Hydrocephalus (1 paper, 2020). Hydrocephalus is an active distension of the ventricular system of the brain resulting from inadequate passage of CSF from its point of production within the cerebral ventricles to its point of absorption into the systemic circulation. "Beyond verifying the occurrence of hydrocephalus, such measurements would highlight case-specific attributes, such as the presence of demyelination, revealed by the overabundance of ECM1, or of an aggressive immune response indicated by the overabundances of vitronectin and complement factors." (PMID 33192320, 2020).
Hyperhidrosis (1 paper, 2023). Abnormal excessive perspiration (sweating) despite the lack of appropriate stimuli like hot and humid weather. "Further research on the utilization of PAI1 in hyperhidrosis will depend on a detailed understanding of PAI1 interaction with vitronectin or the administration sites." (PMID 37542348, 2023).
inflammatory bowel disease (1 paper, 2023). A spectrum of small and large bowel inflammatory diseases of unknown etiology. "However, the function of VTN in inflammatory bowel disease (IBD) remains to be addressed." (PMID 37501933, 2023).
intestinal tumors (1 paper, 2025). "VTN knockout or aPD1 treatment led to reductions in both the number and size of intestinal tumors." (PMID 40538300, 2025).
ischemic disease (1 paper, 2020). Lack of blood supply to an area of the body, resulting in impairment of tissue oxygenation. "The importance of VTN is highlighted, and this knowledge will be helpful in redefining and improving therapeutic efficacy of MSCs in wound healing and ischemic diseases." (PMID 32429996, 2020).
kidney transplant (1 paper, 2021). A surgical procedure in which one or both kidneys from a donor are implanted into a recipient. "Urinary vitronectin levels are a potential stand-alone biomarker to monitor fibrotic changes in kidney transplant recipients in a non-invasive fashion." (PMID 33275196, 2021).
lichen ruber planus (1 paper, 2011). "Vitronectin was shown to bind to in vitro prepared keratin bodies and to keratinocyte derived Civatte bodies in patients suffering from lichen ruber planus." (PMID 21573223, 2011).
limb ischemia (1 paper, 2013). A ischemia that involves the limb. "It is concluded that transient limb ischemia alters the serum protein expression profile in human being, and that reduction of serum contents of complement C3 and vitronectin may represent an important part of the mechanism whereby RIPC confers its protection." (PMID 24363825, 2013). "Furthermore, we confirmed the changes of three proteins of complement C3, vitronectin (75 KDa), and apoA-I after transient limb ischemia by western blotting." (PMID 24363825, 2013).
Listeria infection (1 paper, 2021). "Eight of these genes were similarly inhibited by Listeria infection in PMH: they encode (i) the activating enzyme C1S of the C1 complex, (ii) the central component C3, (iii) the membrane-attack proteins C6 and C8A, and (iv) four complement regulators (C1QTNF6, CFH, CFHR2, VTN)." (PMID 34858876, 2021).
lupus erythematosus (1 paper, 2021). An autoimmune, connective tissue chronic inflammatory disorder affecting the skin, joints, kidneys, lungs, heart, and the peripheral blood cells. "Finally, we analyzed serum samples from healthy controls and patients with osteoarthritis and other rheumatic diseases by nano-LC/Chip MS–MS, confirming the increased expression of VTN(381–397 a.a.) in osteoarthritis as well as in lupus erythematosus and systemic sclerosis." (PMID 33526813, 2021).
malignant glioma (1 paper, 2016). A grade III or grade IV glioma arising from the central nervous system. "Bioinformatics analysis emphasized key roles of integrin β3, hypoxia and vitronectin and their strong correlations with EGFRvIII expression in malignant glioma patient samples in vivo." (PMID 26717039, 2016).
mesothelioma (1 paper, 2009). A usually malignant and aggressive neoplasm of the mesothelium which is often associated with exposure to asbestos. "Some overexpressed genes were confirmed by immunohistochemistry and genes encoding proteins overexpressed in mesothelioma were also overexpressed here (e.g. Ki67, Syndecan 1, Survivin and Vitronectin)." (PMID 19662092, 2009).
metabolic syndrome (1 paper, 2019). A cluster of metabolic risk factors for CARDIOVASCULAR DISEASES and TYPE 2 DIABETES MELLITUS. "Higher blood levels of vitronectin have been associated with the risk of metabolic syndrome and T2D, making it a plausible candidate biomarker of GDM." (PMID 30917176, 2019).
metastatic cancer (1 paper, 2014). A carcinoma which has spread from the original site of growth to another anatomic site. "Vitronectin and IGFBP-5 immunoreactivity was lower while β1 integrin immunoreactivity was higher in the stroma surrounding metastatic cancer tissues, as compared to normal breast and primary cancer stromal tissues." (PMID 25167778, 2014).
metastatic colorectal cancer (1 paper, 2019). "In the cancer development from the early stages to the advanced stages, VTN can be detected in up-regulated levels in a large scale clinical proteomics study in metastatic colorectal cancer, indicating its pro-invasion potential." (PMID 30819137, 2019).
Mitral stenosis (1 paper, 2014). An abnormal narrowing of the orifice of the mitral valve. "Lastly, plasma level of vitronectin was also significantly lower in patients with Mitral Stenosis than control subjects (68.2 ± 6.2 vs. 47.9 ± 4.5 μg/ml, p = 0.01)." (PMID 25379033, 2014). "In our study, plasma vitronectin levels are found to be significantly lower in Mitral Stenosis subjects compared to controls." (PMID 25379033, 2014).